MMP2 (matrix metallopeptidase 2)
Diseases named in the same sentence as MMP2 in open-access papers (continued):
Sharing a sentence is not in itself a finding about the gene and the disease.
glioblastoma (continued). "Interestingly, in orthotopic mouse model of glioblastoma completely devoid of MMP2 activity, tumor vascularity appeared to be less functional with reduction of VEGFR2 expression in tumor vessels and decrease of pericyte coverage." (PMID 26921265, 2016). "Another study suggested that calpain 2 could affect glioblastoma cell invasion by regulating MMP-2 activity." (PMID 23855590, 2013). "Based on these data, we suggest that Bcl-w regulates positively nuclear β-catenin translocation and its binding to TCF-4 in the nucleus, in turn, stimulating the expression of target genes, such as MMP-2 to promote migration and invasiveness in U251 glioblastoma cells." (PMID 23826359, 2013). "Similarly, PIK3R1 knockdown reduced MMP2 and uPA levels in neurospheres, and reduced MMP2 and MMP9 levels in D54 cells, and reduction of the levels of these proteins has been shown to cause reduced migratory and invasive capacity in glioblastoma cells." (PMID 22064833, 2011). "Particularly, the expression of the following genes was affected in A172 cells after 24 h of treatment with TRAIL: VEGF, the MMP-2, the gene encoding TIMP-2, a protein regulating the activity of MMP-2 and SPARC, a protein involved in glioblastoma invasiveness processes." (PMID 16622457, 2006). "Overall, the bulk of data demonstrate that an altered ratio between TIMP-2 and MMP-2 may be related to glioblastoma invasiveness." (PMID 16622457, 2006). "In glioblastoma, the most common and lethal malignant tumor of the central nervous system, resveratrol treatment (40 μM) suppressed the protein expression and enzymatic activity of MMP-2 and significantly inhibited the migration and invasion of cancer cells in vitro." (PMID 39335164, 2024). "Also, the MMP-2 can regulate vascular growth and therefore survival and invasion of glioblastoma." (PMID 38164487, 2024). "MMP-2/-9, which belong to a family of zinc-dependent proteases, play an important role in the degradation of the extracellular matrix during the metastasis of glioblastoma cells by degrading the basement membrane, leading to migration, invasion, and progression of glioblastoma." (PMID 32074974, 2020). "Therefore, CTR-GNPs could be potential therapeutic alternatives against glioblastoma and other MMP-2/-9 and PLD mediated pathologies or conditions." (PMID 32074974, 2020). "However, the overexpression is known to increase MMP-2 levels in glioblastoma." (PMID 29122006, 2017). "Therefore, anosmin-1 increases the proteolytic activities of MMP2/9 and uPA in glioblastoma cells, which may contribute to the ECM remodeling during tumor invasion." (PMID 24189182, 2014). "Interestingly, it has been showed a novel link between NECL-5 and MMP-2 expression in glioblastoma." (PMID 22929570, 2012). "Previously performed studies showed the presence of MMP-2 and MMP-9 in two other culture media of the glioblastoma line, GAMG and 8-MG-BA, and the activity of both enzymes was twice as high in the medium collected from 8-MG-BA." (PMID 40141020, 2025). "Hypoxia has been shown to upregulate MMP-2 mRNA expression in U87, U251, U373, and LN18 glioblastoma cell lines through HIF-1α activation, thereby increasing invasive potential." (PMID 41515435, 2025). "In glioblastoma, remodeling, and degrading of the ECM is observed since Matrix metalloproteinases (MMPs), more specifically MMP-2 and MMP-9, are released into the extracellular space." (PMID 41208963, 2025). "Pre-treatment with anti-VEGF-A antibodies resulted in an upregulation of MMP-2 expression in human U251 glioblastoma multiforme (GBM) xenografts and significantly enhanced the oncolytic effects of a subsequently administered conditionally replicating adenovirus (CRAd-S-pk7)." (PMID 39845957, 2024). "An elevation in the protein levels of MMP1, MMP2, MMP3, and MMP8 was observed in astrocytoma samples, whereas a decrease in the amount of these proteins was noted in the glioblastoma group compared to the control group." (PMID 38474106, 2024).
glioblastoma (continued). "In glioblastomas, it was demonstrated that the interaction of GATA1 and MMP-2 enhanced glioblastoma invasion and migration." (PMID 39684309, 2024). "An increase in the protein levels of MMP1, MMP2, MMP3, and MMP8 was observed in astrocytoma samples, while a reverse trend was noted, with a decrease in the amount of these proteins in the glioblastoma group when compared to the control group." (PMID 38474106, 2024). "Caffeine decreases the invasion of glioblastoma cells In addition, it increases the mRNA and protein expression of tissue inhibitors of metalloproteinase-1 (TIMP-1), whereas MMP-2 is down-regulated." (PMID 39055867, 2024). "In the glioblastoma multiforme (GBM), tricetin reduces MMP-2 production at transcriptional level." (PMID 37560476, 2023). "In glioblastoma, increased MSN expression increased the expression of β-catenin, CD44, ICAM-1, and MMP-2.28." (PMID 37446127, 2023). "For example, in human fibrosarcoma HT-1080 and HCC SK-Hep-1, cells express both MMP2 and MMP9, and glioblastoma T-98G cells express MMP2 but MMP9 only after stimulation with PMA." (PMID 36677584, 2023). "The inhibition of Erk and p38 was then found to be involved in MMP-2 and MMP-9 expression, which revealed naringenin’s ability to inhibit the migration of glioblastoma cells." (PMID 36839156, 2023). "We previously identified matrix metalloproteinase 2 (MMP2) and MMP9 plasma levels as candidate biomarkers of bevacizumab activity in patients with recurrent glioblastoma." (PMID 34980260, 2022). "The involvement of MMP-2 and MMP-9 in the pathogenesis of various kinds of cancers including glioblastoma is well documented." (PMID 35221898, 2022). "Analysis of exosomes from glioblastoma cells showed that they are enriched with the proangiogenic factors VEGF, angiogenin, TGFβ, IL-8, IL-6, MMP2, MMP9, TIMP-1, TIMP-2, and CXCR4." (PMID 35740619, 2022). "Considering this fact, the aim of the current study was to examine the in vitro influence of BV on cell viability and the BV induced secretion of MMP-2 and MMP-9 by glioblastoma cell lines (GAMG, 8-MG-BA) vs. hippocampal cells (HT-22)." (PMID 35221898, 2022). "The aim of this study was to assess the predictive value of MMP2 and MMP9 in a randomized phase III trial in patients with newly diagnosed glioblastoma and to explore their tumor source." (PMID 34980260, 2022). "In particular in human glioblastoma U87 cells, LRP1 promotes cellular migration and invasion by inducing the expression of the matrix metalloproteinase-2 (MMP-2) and MMP-9." (PMID 36012187, 2022). "A prospective local cohort of 38 patients with newly diagnosed glioblastoma was developed for analysis of tumor characteristics by magnetic resonance imaging and measurement of plasma and tumor levels of MMP9 and MMP2." (PMID 34980260, 2022). "The evaluation of the anticancer potential of honey bee (Apis mellifera) venom (BV) consisting of the inhibition of MMP-2 and MMP-9 secretion in a glioblastoma cell culture model was the aim of the study." (PMID 35221898, 2022). "The potential mechanism of radiosensitization was achieved by decreasing the ratio of Bcl-2/Bax, inducing apoptosis in glioblastoma cells, and downregulating the expression of HIF-1α, MMP-2, and Wee1 via the HIF-1α/MMP-2 signaling pathway." (PMID 35744822, 2022). "Though MMPs are not typically viewed as important metabolic modulators, there is emerging evidence that MMP-2, MMP-9, and MMP-14 are potent modulators of cholesterol metabolism, a crucial pathway in glioblastoma growth and invasion." (PMID 34277624, 2021). "It has been reported that naringin inhibits the expression of MMP-2 and MMP-9 in human glioblastoma." (PMID 34054546, 2021). "Furthermore, to investigate whether Sortilin also transduces the anti-MT function of Presenilin1 in glioblastoma cells, we employed western blotting assays to detect Vimentin, N-cadherin, and MMP2 expression when cells were lost or gained function of Presenilin1 and/or Sortilin." (PMID 34781973, 2021).
glioblastoma (continued). "It has also been shown that inhibition of GSK-3 down-regulates the expression of MMP-2 and MT1-MMP in glioblastoma cells and that MMP-2 activation is mediated by the interaction of its pro-form with another metalloprotease, MT1-MMP, and TIMP-2." (PMID 34235177, 2021). "MiR-7 also regulates theexpression of matrix metalloproteinase (MMP)-2 and MMP-9 in coloncancer/glioblastoma cells (Wu etal., 2011; Zeng etal., 2016)." (PMID 32167127, 2020). "MMP2 and MMP9 belonging to the gelatinase subfamily are abundantly expressed and directly related to the degree of glioblastoma malignancy." (PMID 31986121, 2020). "It has been shown that the expression levels of MMP-2 and MMP-9 are much higher in glioblastoma than less aggressive types of brain tumor." (PMID 32089990, 2020). "In glioblastoma cells, lactic acid enhances matrix metalloproteinase-2 (MMP2) levels by upregulating transforming growth factor β2 (TGF-β2) expression and promotes the migration of glioblastoma cells." (PMID 32180770, 2020). "In glioblastoma, the research suggested that miR-708 affects glioblastoma cell proliferation, invasion, and apoptosis through regulating AKt1, CCND1, MMP2, EZH2, Parp-1 and Bcl219." (PMID 33028966, 2020). "One study reported that in human glioblastoma multiforme cell lines, tricetin treatment (80 μM) suppressed cell migration/invasion by enhancing ERK1/2 phosphorylation and inhibited MMP-2 expression." (PMID 32397656, 2020). "In addition, α-H also increased TIMP-1 expression and inhibited mRNA expression and protein levels of MMP-2 and MMP-9 and hence their enzymatic activities, which may be associated to the reduced migration and invasion capacities of glioblastoma cells exerted by α-H." (PMID 31551765, 2019). "In glioblastoma, VEGF is located upstream of MMP-2 in the ERK/MAPK pathway such that VEGF affects MMP-2 expression and therefore tumor cell proliferation and neovascularization." (PMID 31757094, 2019). "Here, we also found that the activities of MMP-2 and MMP-9 are involved in glioblastoma cells’ invasion, as the activities of MMP-2 and MMP-9 were impaired in CrataBL-treated cocultures, but remained unchanged in CrataBL-treated MSC and U87 cell monocultures." (PMID 31167364, 2019). "In glioblastoma cell lines, ectopic PAX6 expression downregulates matrix metalloproteinase-2 (MMP2) and suppresses invasiveness." (PMID 29716531, 2018). "In Western blot analysis, the expression levels of MMP-2 and MMP-9 were decreased in the glioblastoma cells following treatment with HES in a dose-dependent manner." (PMID 29181405, 2017). "MMP-2 and MMP-9 are highly expressed in glioblastomas, and the expression increases with tumor development at both the messenger RNA and protein levels." (PMID 29285298, 2017). "Measurements of MMP-2 intensity increased with tumor grade, and MMP-2 expression was found to be significantly higher in glioblastomas compared to normal brain tissue (p<0.001), diffuse astrocytomas (p<0.001) and anaplastic astrocytomas (p<0.05)." (PMID 28234925, 2017). "In one study, Polish honeys were shown to decrease MMP-2 and MMP-9 activity in the glioblastoma cell line U87MG." (PMID 28933410, 2016). "Several studies address the fact that MMPs especially MMP-2 and MMP-9 overexpressed in glioblastoma cells compared with normal brain tissue." (PMID 27026929, 2016). "Studies using glioblastoma cells also showed that MDA-9 increased the activation of c-Src, p38 MAPK and nuclear factor kappa B (NF-κB), which enhanced expression of matrix metalloproteinase 2 (MMP2) and the secretion of interleukin-8 (IL-8)." (PMID 27863394, 2016). "The US clinical trial “MMP2, MMP9 and NGAL as Biomarkers for Glioblastoma (GBM) Biomarkers for the Prognosis of Glioblastoma (NCT01493219)” has been sponsored by University of Nebraska started since 2011." (PMID 27022952, 2016).
glioblastoma (continued). "Last, FOXM1 stimulates self-renewal, tumorigenicity and invasiveness of glioblastoma stem-like cells by transactivating a number of molecules, including IPO7 (importing-7), CDC20, PDGF-A, ANXA1, MMP-2 and VEGF." (PMID 27259253, 2016). "A comparison of tumor subtypes demonstrated that CD133+ glioblastoma cells had a lower incidence of cell apoptosis in the tumor tissue and higher protein expression levels of Oct4, Sox2, PCNA, EGFR, Ang2, MMP2 and MMP9 compared with CD133− cells." (PMID 23251243, 2013). "The CD133+ glioblastoma cell induced-tumor tissue expressed significantly higher levels of Oct4, Sox2, PCNA, EGFR, Ang2, MMP2 and MMP9 proteins compared with the CD133− glioblastoma cell induced-tumor tissue (P<0.05)." (PMID 23251243, 2013). "Because of the high expression levels of MMP-2, we evaluated the binding capabilities of M/D-CTX-Fcs on the surface of A172 glioblastoma cells." (PMID 23304519, 2012). "The human glioblastoma cell lines A172, U87MG and U373MG expressed substantial amounts of the MMP-2, which were decreased after treatment with TRAIL." (PMID 16622457, 2006). "Neither Ctx nor its fragments inhibited MMP-2 enzymatic activity, however, glioblastoma cellular migration was inhibited." (PMID 40791509, 2025). "Inhibition of cellular migration without inhibition of MMP-2 activity warrants further study into the possible targets of Ctx expressed in glioblastoma." (PMID 40791509, 2025). "In addition, STAT3 was shown to be a positive regulator of HIF1α, VEGF, MMP-2 and TWIST in hypoxic glioblastoma and its suppression induced proliferation arrest and apoptosis in glioblastoma cells." (PMID 38654280, 2024). "Moreover, it was found that quercetin exerted promising activity in vitro against human glioblastoma cells (U251) by reducing the expression of matrix metallopeptidases MMP-9 and MMP-2." (PMID 39478959, 2024). "Interestingly, expressions of MMP2, chloride voltage-gated channel 3 (CLCN3), and annexin A3 (ANXA3) seem to be indispensable for the binding of CLTX to glioblastoma cells." (PMID 36721153, 2023). "Of note, the MMP2 plasma level was lower in glioblastoma patients than in aneurysm or control patients, was not correlated with MMP2 tumor expression, and did not vary during the perioperative time." (PMID 34980260, 2022). "Finally, melatonin antagonized hypoxia-mediated migration and invasion by suppressing HIF-1α, matrix metalloproteinase 2 (MMP2) and VEGF in glioblastoma U251 and U87 cells." (PMID 34208645, 2021). "Furthermore, the secretion of MMP-2/-9, which is induced by PLD, contributes to the migration and invasion of glioblastoma cells." (PMID 32074974, 2020). "Moreover, MMP-2 and MMP-9, the members of the metalloproteases family, which were frequently involved in glioblastoma invasiveness, were downregulated along with the reduction of HMGN5 in glioblastoma cells." (PMID 32596388, 2020). "We further examined whether CTR-GNPs can suppress the protein expression of MMP-2/-9 and PLD1/2 in human U87 glioblastoma cells." (PMID 32074974, 2020). "miR-223 is another well-recognized oncogenic miRNA, which, in glioblastoma, promotes growth and invasion of tumor cells by targeting the tumor suppressor PAX6, exerting its function by inhibiting the expression of metalloproteases MMP2 and MMP9." (PMID 33287106, 2020). "Moreover, future research is warranted to explore and develop CTR-GNPs as inhibitors against the specific isoforms of MMP-2/-9 and PLD that contribute to glioblastoma." (PMID 32074974, 2020). "Luteolin in glioblastoma cell lines U251MG and U87MG decreases levels of MMP-2 and MMP-9 protein." (PMID 32102219, 2020). "Our results revealed that SH inhibited proliferation by inducing cell cycle arrest and attenuated the metastasis of human glioblastoma U87 and SF767 cells by suppressing the expression of MMP-2/-9 and reversing endogenous and exogenous EMT in vitro and/or in vivo." (PMID 29538296, 2018).
glioblastoma (continued). "Additionally, suppression of MMP-2 and MMP successfully inhibited or delayed glioblastoma invasion and migration in vitro and in vivo." (PMID 29423667, 2018). "Recently, it was reported that melatonin inhibits HIF-1α protein and suppress the expression of matrix metalloproteinase 2 (MMP-2) and VEGF by means of its antioxidant activity, reducing the invasion and migration mediated by hypoxia, of U251 and U87 glioblastoma cells." (PMID 27199982, 2016). "Furthermore, both MMP-2 and MMP-9 activities can also be measured in the CSF, and MMP-9 activity in particular was noted to correlate with disease activity in recurrent glioblastoma." (PMID 27876012, 2016). "It was reported that down-regulated uPA expression could inhibit AKT/mTOR signal pathway in glioblastoma cells, and AKT-mTOR signal pathway could modulate MMP-2 expression important for cleavage of the Laminin 5γ2 which was essential in the VM formation." (PMID 26992227, 2016). "Moreover, using a human glioblastoma cell line model, it was demonstrated that up-regulation of TIMP-2 promotes MMP-2 activation and subsequent glioblastoma cell invasion." (PMID 26361584, 2015). "We also noticed that the transcription of key genes involved in inflammation, proliferation, angiogenesis and extracellular matrix remodelling (including MMP2, HIF1A, IL1B, IL1A, IL1R1, MMP2, VEGFA), processes vital to glioblastoma development, were down-regulated by RND3 knock-down." (PMID 26132659, 2015). "A study carried out in the invasive glioblastoma cells showed that increase in local TIMP-2 concentrations has the effect of initially stimulating MMP-2 activation, whereupon exceeding amounts of TIMP-2 are inhibitory to MMP-2 activation." (PMID 24591757, 2014). "MiR-451 was found to directly impact glioblastoma cell proliferation, invasion, and apoptosis by down regulating the expression of Akt1, CyclinD1, MMP-2, MMP-9 and B-Cell CLL/lymphoma 2 (Bcl-2), however, no direct interaction of any of these mRNAs were found." (PMID 24670365, 2014). "Tumor necrosis factor-related apoptosis-inducing ligand (TRAIL) inhibits messenger RNA (mRNA) expression of VEGF, together with matrix metalloproteinase-2 (MMP-2) and tissue inhibitor of matrix metalloproteinases-2 (TIMP-2) in different human glioblastoma cell lines." (PMID 24520293, 2014). "Notably, CD133+ glioblastoma cell-induced tumors expressed higher levels of EGFR, Ang2, MMP2 and MMP9 proteins compared with CD133− cell-induced tumors, suggesting that CD133+ cell-induced tumors have a higher degree of malignancy." (PMID 23251243, 2013). "Consequently, the reduction of MMP2 and MMP9 by Ad-CALR/MAGE-A3 will attenuate the metastatic potency of glioblastoma cells." (PMID 22293781, 2012). "Moreover, our analyses revealed a downregulation of HEF1/NEDD9 and of metallo-matrixproteases pro-MMP1 and pro-MMP2 in SOX2-depleted U343-MG and U373-MG glioblastoma cells." (PMID 22070920, 2011). "SIM2 regulates the expression of MMP-2 and TIMP-2, which drive its role in glioblastoma cells." (PMID 22174909, 2011). "In addition, TRAIL potently suppresses the expression of tissue remodelling factors, such as MMP-2 and TIMP-2, as well as of those promoting glioblastoma invasiveness, such as SPARC." (PMID 16622457, 2006). "Moreover, the expression of MMP-2, its inhibitor TIMP-2 and the tumour invasiveness-related protein SPARC were effectively inhibited by TRAIL in glioblastoma cell lines." (PMID 16622457, 2006). "Curcumin dose-dependently downregulates the expression of EphA2, PI3K, and MMP2 to block the EphA2/PI3K/MMP-2 signaling pathway, thereby suppressing ECM remodeling as well as glioblastoma cell migration and invasion, ultimately disrupting VM formation in glioblastoma." (PMID 41019994, 2025).